OCEL1 (occludin/ELL domain containing 1)
Synonyms: FLJ22709; FWP009; S863-9
Tractability: No criterion of Open Targets' tractability assessment is met for any kind of drug.
Gene: Protein-coding gene on chromosome 19 (17,226,198 to 17,229,219, forward strand). Ensembl gene ENSG00000099330.
Subcellular location (Human Protein Atlas): Golgi apparatus
Gene Ontology:
Biological process: bicellular tight junction assembly
Cellular component: apical plasma membrane; bicellular tight junction; cytoplasmic vesicle
Genetic constraint (gnomAD): Loss-of-function variants: 24 observed, 29.2 expected, observed/expected ratio (o/e) 0.82, 90% interval 0.59 to 1.16. The upper end of that interval is the gene's LOEUF score, 1.16, which puts it in group 5 of 6, group 1 being the genes least tolerant of losing a copy. Missense variants: 402 observed, 335.4 expected, observed/expected ratio (o/e) 1.2, 90% interval 1.1 to 1.3. Synonymous variants: 172 observed, 138.25 expected, observed/expected ratio (o/e) 1.24, 90% interval 1.1 to 1.41.
Homologues: Orthologues: chimpanzee OCEL1 (99% identical), macaque OCEL1 (94% identical), dog OCEL1 (68% identical), pig OCEL1 (59% identical), rat Ocel1 (49% identical), mouse Ocel1 (47% identical), zebrafish marveld2l (25% identical), Drosophila melanogaster Su(Tpl) (19% identical), zebrafish si:ch211-13k12.2 (19% identical), zebrafish zgc:154006 (12% identical), Caenorhabditis elegans ell-1 (12% identical). Paralogues in human: MARVELD2 (32% identical), ELL (20% identical), ELL2 (19% identical), OCLN (18% identical), ELL3 (17% identical).
Diseases named in the same sentence as OCEL1 in open-access papers:
OCEL1 is named in the same sentence as 2 diseases in open-access papers, as found by Europe PMC text mining. Sharing a sentence is not in itself a finding about the gene and the disease. The quoted sentences say what the papers report.
Aicardi syndrome (1 paper, 2017). Aicardi syndrome is a rare neurodevelopmental disorder defined by the triad of agenesis of the corpus callosum (total or partial), typical chorioretinal lacunae and infantile spasms that affect almost exclusively females. "It has been reported recently that de novo variants in TEAD1 and OCEL1 each may cause Aicardi syndrome in a single individual of a small cohort of females with this clinical diagnosis." (PMID 28361097, 2017). "A comprehensive evaluation of the described individuals with TEAD1 and OCEL1 variants by clinicians experienced with the diagnosis of Aicardi syndrome would also be helpful to distinguish any subtle phenotypic anomalies that might be specific to subjects harboring variants in these autosomal genes." (PMID 28361097, 2017). "To investigate this further, we sequenced TEAD1 and OCEL1 coding regions using DNA from 38 clinically well‐characterized girls with Aicardi syndrome." (PMID 28361097, 2017). "Although TEAD1 and OCEL1 may be rare causes of Aicardi syndrome, it is also possible that these genes may contribute to phenotypes that overlap with characteristics of Aicardi syndrome and that the phenotypic characterization of Aicardi syndrome requires refinement." (PMID 28361097, 2017). "However, OCEL1 is highly expressed in the eye, retina, and the brain – regions that are most affected in girls with Aicardi syndrome." (PMID 28361097, 2017).
OCEL1 also shares sentences with these, for which no sentence is quoted: breast carcinoma (1 paper).